HIF1A (hypoxia inducible factor 1 subunit alpha)
Diseases named in the same sentence as HIF1A in open-access papers (continued):
Sharing a sentence is not in itself a finding about the gene and the disease.
cancer (continued). "Notably, the involvement of HIF-1α, a redox-sensitive protein, in initiating early redox hypoxia-dependent processes during epithelial-mesenchymal transition (EMT) in cancer cells is also significant." (PMID 39812050, 2025). "The roles of LDH-5, HIF-1α, TRIB3, and hypoxia-related lncRNAs highlight the complex connections between cellular responses to low oxygen levels and cancer progression, underscoring the need for further investigation into these factors as potential therapeutic targets or prognostic indicators." (PMID 40322886, 2025). "Furthermore, our study revealed significant modifications in HIF-1α and SOD2, two essential components involved in cancer cell survival and progression, particularly under conditions of hypoxia and oxidative stress." (PMID 39860164, 2025). "These exosomes contain specific miRNAs, such as miR-20a-5p and miR-421, which promote IL-6 production and pancrea1ic cancer progression, respectively, by regulating the SIRT3/H3K9ac/HIF-1α axis.The cargo of CAF-derived exosomes is crucial for their effectiveness in cancer progression." (PMID 40038745, 2025). "Similar to other USP29 substrates c-MYC, HIF1α and Snail1, AURKB deregulation often occurs in cancers, implying that USP29 may become a potential target for cancer treatment." (PMID 38233848, 2024). "Similarly, the combination of digitoxin and sorafenib has been reported to suppress p-ERK, hypoxia inducible factor (HIF)-1α, HIF-2α, and VEGF expression, contributing to apoptosis in cancer cells." (PMID 38527038, 2024). "Furthermore, LINK-A’s interaction with several key signaling pathways, including HIF1α, PIP3-AKT, cAMP/PKA, TGF-β, and ERK, underscores its significant impact on cancer biology, highlighting LINK-A as a potential target for further exploration." (PMID 38645412, 2024). "As the PI3K/AKT pathway is common in various cancers, we verified whether USP39 could stimulate PI3K/AKT/HIF-1α signaling to accelerate glycolysis." (PMID 38459014, 2024). "Recent findings indicate that neddylation, pivotal for cancer cell migration via the PI3K-Akt pathway, when inhibited, upregulates HIF-1α, modulating EMT-activator ZEB1 in various cancer cell lines, underscoring its significant role in cancer progression and metastasis." (PMID 38191508, 2024). "HIF-1α induces the expression of numerous genes related to angiogenesis, growth and survival, invasion and metastasis, glucose metabolism, epithelial–mesenchymal transition (EMT), immune evasion, and resistance to various cancer treatments." (PMID 38799423, 2024). "In contrast, the loss of HIF‐1α does not impact NSCLC progression, highlighting the distinct functional roles of HIF isoforms in cancer biology." (PMID 39415849, 2024). "PI3K/AKT/mTOR and hypoxia/HIF1α signaling, in collaboration with other signaling pathways, induces the expression of EMT-TF genes (i.e., SNAIL, ZEB1/2, and TWIST1/2) and activates EMT in cancers, including PCa." (PMID 38792011, 2024). "Moreover, the miR-142/HIF-1α axis regulates key markers of epithelial-mesenchymal transition (EMT), including E-cadherin, VEGF-C, and Vimentin, which play crucial roles in cancer metastasis and progression." (PMID 38927885, 2024).
cancer (continued). "Moreover, it was recently reported that under normoxia, HIF-1α is transiently expressed during the G1 phase in an AMP-activated protein kinase (AMPK)-dependent manner and in cancer cells grown under nutritional stress contributing, thus, to their survival." (PMID 38300329, 2024). "Although an early report mentioned a relationship between LAMC1 and hypoxia, our current study clarified the regulatory relationship between HIF-1α and LAMC1 expression, which expands our understanding of the molecular mechanism of ECM remodeling in the hypoxic microenvironment of malignant tumors." (PMID 38678297, 2024). "The downregulation of HIF1A and COPS5 has been shown to inhibit the proliferation and malignant behaviors of cancer cells, suggesting that inhibitors targeting the two proteins may have potential as anticancer therapeutics." (PMID 38360878, 2024). "Accordingly, cancer cells that accumulate lactate due to “aerobic glycolysis” have reduced PHD2 activity, reduced proteasomal degradation of HIF-1α, and hence increased levels of HIF-1α protein." (PMID 38339256, 2024). "In cancer, VEGF and HIF-1α are closely related, with HIF-1α promoting VEGF to drive metastasis." (PMID 39199245, 2024). "HIF1α increases cellular lipid uptake by inducing the expression of fatty acid-binding proteins (FABPs) 3 and 7 (FABP3 and FABP7) in glioblastoma, which are both required for cancer cell survival in hypoxic conditions." (PMID 39284708, 2024). "In addition, it was shown by promoter analysis that the expression of many cancer stem cell (CSC)-related genes such as TERT, BMI1, BSG (CD147), and PROM1 (CD133) was under the control of SP1, HIF1A, and MYC." (PMID 39590335, 2024). "Thus, HIF-1α-IN-2 is a promising new therapeutic agent with potential applications in the treatment of TNBC and other cancers." (PMID 39194515, 2024). "Contrarily, it was shown that miR-98-5p is downregulated in ovarian cancer tissues, and its mitigative effects on cancer are hampered by overexpressed lncRNA DSCR8, which is known to promote cancer progression through a highlighted lncRNA DSCR8/miR-98-5p/STAT3/HIF-1α axis." (PMID 38872210, 2024). "Hypoxia-inducible factor 1-alpha (HIF-1α) can indirectly stabilize and activate the transcription of many genes involved in copper metabolism, including those controlling CTR1, thereby contributing to higher copper levels in cancer cells." (PMID 39330493, 2024). "HIF1α, MMP9 and β catenin are well known as cancer malignancy markers." (PMID 39273283, 2024). "Consequently, Mn-CuS@BSA-FA emerges as a NIR-responsive glycolytic inhibitor, with potential applications in cancer therapy, due to its ability to suppress cellular ATP levels, LDHA activity, and HIF-1α expression." (PMID 39479443, 2024). "Inhibition of NRF2 in cancer cells has been reported to suppress HIF activity through multiple molecular events, including direct regulation of HIF-1α expression by NRF2, HIF-1α stabilization by the NRF2 target NQO1 and TRX1, and HO-1-driven CO and miRNA expression." (PMID 38424190, 2024). "Based on the findings above, HIF‐1α and EZH2 may play a functionally complementary carcinogenic role in cancer development and may account for single‐drug resistance and poor therapeutic efficacy." (PMID 38072662, 2024). "Additionally, in human cancers, LRRK2 phosphorylates HIF-1α at Ser797, which enhances HIF-1α‘s binding affinity to its cofactor p300, thereby increasing the production of HIF-1α target genes." (PMID 39408813, 2024). "Activation of HIF1α may alter cancer cell metabolism and mitochondrial state, suggesting indirect mitochondrial effects by the LINK-A-HIF1α axis as a potential research area." (PMID 38645412, 2024). "DNA methylation also upregulates HIF-1α, enhancing HIF pathway signaling in cancer." (PMID 39119332, 2024).
cancer (continued). "HIF-1α induces the transcriptional activation of the cysteine transporter (SLC7A11) and the regulatory subunit of glutamate–cysteine ligase, known as GCLM, in order to enhance the synthesis of glutathione in specific cancer types." (PMID 38399410, 2024). "Thus, these miRNAs either positively or negatively affect cancer progression by targeting both cancer cells per se and the cancer microenvironment via modulation of all three of SP1, MYC, and HIF1A." (PMID 39590335, 2024). "HIF1α/HIF2α induce ALKBH5 (alkB homolog 5, RNA demethylase) expression during hypoxic conditions that demethylate Sox2 mRNA (m6A-modified mRNAs), leading to Sox2/CD133 upregulation and maintenance of cancer stem-like traits." (PMID 37922108, 2024). "(ii) in fact, some carcinogenic signaling pathways, such as HIF-1α and RAS/PI3K/AKT, may generate drug resistance by enhancing aerobic glycolysis in cancer cells (the “Warburg effect”)." (PMID 38581001, 2024). "Also, it inhibits angiogenesis and metastasis through decreasing HIF-1α activity, leading to a reduction in JNK-1 phosphorylation which in turn leads to stopping of VEGF-mediated proliferation and decreases cancer growth." (PMID 39478959, 2024). "These therapeutics also drive cancer cell heterogeneity and the emergence of chemorefractory clones with metastatic properties acquired e.g. via EMT by upregulation of transcription factors like HIF1α, Snail, Slug or Twist 270,71." (PMID 39592661, 2024). "Furthermore, this review aims to elucidate the intricate interplay between HIF1α, SMURF2, and the TME, shedding light on their significance in shaping tumorigenesis and cancer progression." (PMID 39697237, 2024). "Additionally, HIF-1α promotes the synthesis of glucose transporter 1 (GLUT1), which provides more glucose for the energy metabolism of cancer cells." (PMID 39061859, 2024). "Typically, MCP-1 (lactate importer) is more commonly expressed under physiological conditions, while cancer cells upregulate the MCP-4 (lactate exporter), as a consequence of HIF1-α activation, to overcome intracellular dysregulations triggered by a build-up of lactate." (PMID 39282472, 2024). "HIF-1α promotes cancer cell growth and angiogenesis via hypoxic or non-hypoxic pathways, and TNF R1 is involved in TNF signaling pathways, which regulate cell death." (PMID 39382942, 2024). "Alterations in cancer and TME with increased HIF-1α in hypoxia." (PMID 38544822, 2024). "Since MYH9 stabilized HIF-1α and promoted LR and p-MYH9 specifically interacted with HIF-1α, we wondered whether p-MYH9 could be an effective target for reversing LR and suppressing cancer stemness." (PMID 39300073, 2024). "In certain cellular contexts, such as cancer cells, the accumulation of ROS and succinate resulting from dysregulation of mitochondrial metabolism can inhibit the activity of PHD, consequently increasing the stability of the HIF-1α protein." (PMID 38880883, 2024). "Immunofluorescence (IF) coexpression of HIF1A and SOX9 (n = 3, sourced from the National Cancer Center) confirmed our hypothesis to some extent." (PMID 39033089, 2024). "Moreover, PGK1 is a transcriptional target of HIF-1α and enhances HIF-1α activity, forming a feedback loop that promotes cancer metastasis." (PMID 39590296, 2024). "Therefore, the data overall indicated that M4N was a dual inhibitor for SP1 and HIF1A and occasionally worked as an inhibitor for MYC in certain cancers." (PMID 39590335, 2024). "These pathways include but are not limited to HIF-1α/VEGF/VEGFR2/PI3K/AKT, Wnt/β-catenin, JNK1/STAT3, and MAPK/AP-1, which may provide some new active ingredients or targets for future cancer treatment." (PMID 38611849, 2024).
cancer (continued). "If the ratio of VEGF-A to HIF-1α shifts to HIF-1α, metabolic adaptation in molecular subtypes of the cancer cells and the pathological formation of blood vessels in the hypoxic microenvironment may be indicated." (PMID 39199545, 2024). "We established that 100–150 μM CoCl2 could be used to stimulate HIF-1α and growth factor receptors such as HER2 and the adhesion molecule EpCAM in order to grow and maintain CTCs isolated from the blood of cancer patients." (PMID 36879003, 2023). "Interestingly, in all of these studies, three TFs, namely SP1, HIF1A, and MYC, were among the factors that participated in the cancer regulatory network." (PMID 37998757, 2023). "We expected that the treatment of rhIL-21 in the co-culture of HIF-1α-expressed HCC SK-Hep1 cells and NK-92 cells could enhance the effector function of NK cells against cancer cells compared to the treatment of IL-6 antibody alone." (PMID 37501379, 2023). "In addition to regulating HIF1α expression through inhibition of FIH1, miR-24 further aids cancer cells by targeting pro-apoptotic BCL2-like 11 (BCL2L11, Bim) to promote resistance towards chemotherapy-driven apoptosis in breast CSCs." (PMID 37583933, 2023). "Functional studies and gene expression determination confirm that MIAT knockdown not only affects short- and long-term survival and the apoptosis of leukemic cells but also plays a pivotal role in the alteration of key genes involved in cancer, including c-MYC and HIF-1A." (PMID 37624039, 2023). "This assertion is further corroborated by the observation that most of our cancer samples were HIF-1α-positive despite the absence of necrosis." (PMID 37166494, 2023). "Previously, we demonstrated that 300 nM tipifarnib, which is an FTI, reduces HIF-1α expression in triple-negative breast cancer cells and suppresses migration, cancer stemness, and epithelial-to-mesenchymal transition regardless of RAS expression." (PMID 37511305, 2023). "Preclinical studies have demonstrated that CGA exerts antitumor activity, possibly because of its ability to inhibit tyrosine kinases, matrix metalloproteinases, HIF-1α, and AKT, and more importantly to repolarize macrophages and enhance anti-cancer immunity in glioma." (PMID 37366368, 2023). "Targeted inhibition of HIF-1α and HIFAL effectively inhibits cancer." (PMID 37204526, 2023). "In addition to regulation of cell proliferation and apoptosis, it can affect cancer metabolism and angiogenesis through modulation of a number of targets including GLUT1, VEGFA, and HIF1α." (PMID 37204522, 2023). "In addition, KT suppressed the expression of HIF1α, MMP-2, and MMP-9, which also play a significant role in bone metabolism and metastasis of cancer." (PMID 36674719, 2023). "To evaluate the anti-cancer drug resistance effects of macrophages, we investigated the expression levels of COX2, HIF-1α, growth factors and multidrug resistance genes, cell viability, apoptosis rates, and cell cycle arrest in canine MGT cells co-cultured with DH8248,49." (PMID 37369757, 2023). "In the case of hypoxia, the expression of HIF-2α (but not HIF-1α) mRNA is up-regulated only in GSCs, but not non-stem cancer cells or fetal human neural progenitor cells." (PMID 39872059, 2023).
cancer (continued). "Additionally, the increased levels of HIF1α and FGF2 indicated activation of survival pathways in cancer cells and possible stimulation of EMT, which would constitute unwanted effects of combinational treatment." (PMID 37834191, 2023). "HIF-1α can induce the expression of HGF and c-Met in various cancer cells." (PMID 36901857, 2023). "Existing evidence suggests that targeting HIF-1α is not sufficient to disrupt the metabolism of cancer cells, which highlights the need for further investigation of anti-HIF-1 drugs, including their combination with other therapeutic approaches." (PMID 37568758, 2023). "Moreover, HOXC-AS3 is functionally dependent on HIF-1α, and knockdown of HOXC-AS3 can significantly inhibit the cancer-promoting effect of HIF-1α." (PMID 37204526, 2023). "For this purpose, resveratrol not only acts as pro-apoptotic (caspase-3) but also induces its effect against inflammation (NF-kB), vascularisation (VEGF), and cancer stem cells (CD44, CD133, ALDH1), and also targets the β1-integrin/HIF-1α axis that is highly pronounced in CRC cells." (PMID 36902421, 2023). "This led to the downregulation of TGFβ-responsive genes, including vascular growth factor A/B (VEGFA/VEGFB), hypoxia-inducing factor 1α (HIF-1α), and thrombospondin 1 (TSP1), all of which play crucial roles in various aspects of cancer progression such as angiogenesis, invasion, and metastasis." (PMID 37894372, 2023). "In hematological malignancies, HIF-1α was required for the maintenance of cancer stem cells in AML, and the downregulation of HIF-1α could effectively eliminate the activity of AML colony-forming unit." (PMID 37124944, 2023). "Interestingly, HIF-1α and MMP-13 were localized in cancer cells and exosomes when cells were exposed to hypoxia." (PMID 38069210, 2023). "HIF-1α is commonly expressed in tumors, but the role of HIF-1α in cancer is not fully understood." (PMID 36334237, 2023). "Moreover, HIF-1α directly regulates the transcription of CXCR4, a chemokine receptor involved in cancer cell migration, invasion and in the maintenance of CICs in different solid tumors." (PMID 37838700, 2023). "Here, we show that COPD alters the protein content of EVs and that HIF-1α/CXCR4 axis activation caused by COPD-EVs in non-tumorigenic epithelial cells leads to the acquisition of malignant features and cancer progression." (PMID 37838700, 2023). "Finally, USP29 ubiquitinase is a potential novel target for cancer therapy as it provides an upstream hub for MYC and HIF1α." (PMID 37443779, 2023). "In addition to the well-known influence of hypoxia on HIF1α at the level of protein stability, transcriptional regulation of HIF1A plays a considerable role in cancer." (PMID 37098526, 2023). "HIF-1α is the main stimulus for elevated VEGF, FGF, and PDGF production in cancer." (PMID 36984763, 2023). "In addition to CCND1, several other cancer-relevant genes, including MCL1, BCL2L1, CDC25, FAS, and HIF1A, were among the common genes." (PMID 36807142, 2023). "In the literature, two hypotheses have been proposed as involved in this phenomenon: under normoxic conditions, SCF/c-Kit binding increases expression of HIF-1α through the PI3K/Akt and Ras/MEK/ERK pathways, even if in an experimental in vitro model of cancer." (PMID 36830966, 2023). "Acqusition of aggressive phenotypes observed in hypoxic tumors is mainly attributed to hypoxia-inducible factor-1α (HIF-1α), which plays a central role in management of hypoxic stress: HIF-1α transcriptionally provides hundreds of target proteins for adaptation of cancer cells." (PMID 37777750, 2023). "LncRNA versican (VCAN)-AS1 promotes breast cancer cell migration, invasion, and EMT by working as a competing endogenous RNA to inhibit miR-106a-5p, which cancer cell progression via targeting signal transducer and activator of transcription 3 (STAT3) and inhibiting the STAT3/HIF1α axis." (PMID 37583933, 2023).